GMIP (GEM interacting protein)
Diseases named in the same sentence as GMIP in open-access papers:
GMIP is named in the same sentence as 17 diseases in open-access papers, as found by Europe PMC text mining. Sharing a sentence is not in itself a finding about the gene and the disease. The quoted sentences say what the papers report.
lung cancer (4 papers, 2020 to 2025). A malignant neoplasm involving the lung. "In lung cancer, overexpression of GMIP was associated with longer survival; in the null mice model with a xenografted tumor of A549 cells, GMIP treatment has once been proved to induce autophagy and reduce tumor growth." (PMID 35237298, 2021). "GMIP expression attenuates lung cancer cell migration, and its over-expression is associated with longer survival of lung cancer patients." (PMID 33227088, 2020). "This research presents us the RASSF1C/PIWIL1/piRNA axis, modulating the Gem Interacting Protein (GMIP) mRNA expression by DNA methylation in lung cancer, and thus affecting the migration of cancer cells." (PMID 36882835, 2023). "TBX5, SPRED2, and NKX2-1 have been shown to exhibit tumor suppressor functions in lung cancer, while GMIP function has yet to be determined in cancer cells." (PMID 33227088, 2020). "Consistent with a role for GMIP as an inhibitor of neuronal cell migration, we found that over-expression of GMIP in lung cancer cells appears to also attenuate lung cancer cell migration." (PMID 33227088, 2020). "In this study we report for the first time that GMIP does display some characteristics of a novel tumor suppressor gene in lung cancer." (PMID 33227088, 2020). "Based on our Kaplan–Meier and mRNA expression analyses identifying GMIP as a potential tumor suppressor, we assessed the impact of over-expressing GMIP on lung cancer cells proliferation and migration." (PMID 33227088, 2020). "We also assessed GMIP mRNA expression in human lung cancers and matched normal tissues and found that GMIP mRNA expression is down-regulated in 56% of lung cancer samples (n = 23)." (PMID 33227088, 2020). "Kaplan–Meier analyses show that high expression of both GMIP and NKX2-1 is significantly associated with higher lung cancer patient survival." (PMID 33227088, 2020). "It has been previously suggested that TBX5, SPRED, and NKX2-1 may function as tumor suppressors in lung cancer, while nothing is known about the function of GMIP in any human cancer." (PMID 33227088, 2020). "This provides further support for the hypothesis that GMIP could be regulated by a PIWIL1-piRNA complex in lung cancer cells." (PMID 33227088, 2020). "In addition, they also suggest that A4GALT and GMIP may be new biomarkers for lung cancer that will be the focus of future investigations." (PMID 33227088, 2020). "Thus, GMIP could potentially be a novel lung cancer tumor suppressor." (PMID 33227088, 2020). "We assessed GMIP mRNA expression in lung cancer cells overexpressing RASSF1C and found that GMIP mRNA is down-regulated in cells overexpressing RASSF1C compared to cells overexpressing the control vector backbone." (PMID 33227088, 2020). "Additionally, through single‐cell RNA sequencing analysis of 12,346 single cells from 20 non‐small cell lung cancer (NSCLC) patients in the GSE99254 dataset, we observed that GMIP is primarily expressed in monocytes/macrophages and CD8+ T cells." (PMID 40275529, 2025). "While GMIP overexpression did not affect cell proliferation (data not shown), GMIP overexpression in the lung cancer cell lines A549 and NCI-H1299 resulted in a significant decrease in cell migration." (PMID 33227088, 2020).
breast carcinoma (2 papers, 2017 to 2025). "The results of the CCK‐8 and colony formation assays showed that GMIP knockdown significantly inhibited the proliferation of breast cancer cells." (PMID 40275529, 2025). "Our experimental findings demonstrated that GMIP knockdown significantly inhibited breast cancer cell proliferation and migration, suggesting its oncogenic potential." (PMID 40275529, 2025). "GMIP is identified as a promising oncological biomarker, particularly in breast cancer, with potential therapeutic implications." (PMID 40275529, 2025). "Our findings highlight GMIP's pivotal role in breast cancer cell survival and migration." (PMID 40275529, 2025). "In vitro assays confirmed GMIP's functional relevance in breast cancer." (PMID 40275529, 2025).
endometrial carcinoma (2 papers, 2020 to 2025). A malignant tumor arising from the epithelium that lines the cavity of the uterine body. "In endometrial cancer, GMIP's differential expression has been confirmed via immunohistochemistry and Western blot, with upregulation correlating with increased tumour invasiveness and metastasis." (PMID 40275529, 2025). "Recent studies have predicted a correlation between GMIP and endometrial cancer, suggesting the potential of GMIP as a novel cancer marker." (PMID 40275529, 2025). "‘mutation’ is the most common type of alteration, with the highest rate of GMIP alterations observed in endometrial cancer patients." (PMID 40275529, 2025). "We should mention that GMIP is over-expressed in endometrial carcinoma and it has been suggested as a potential biomarker among several genes identified endometrial carcinoma." (PMID 33227088, 2020). "However, the role of GMIP in endometrial carcinoma has not been determined yet." (PMID 33227088, 2020).
hepatocellular carcinoma (1 paper, 2025). A malignant tumor that arises from hepatocytes. "Research has shown that DLC1, as a gene from the same family as GMIP, acts as a tumour suppressor in hepatocellular carcinoma and provides evidence supporting the hypothesis that DLC1 inhibits cancer cell growth by negatively regulating Rho protein activity." (PMID 40275529, 2025). "Similar to GMIP, DLC1—another family member—acts as a tumour suppressor in hepatocellular carcinoma by regulating Rho protein activity." (PMID 40275529, 2025).
Insulin resistance (1 paper, 2026). Increased resistance towards insulin, that is, diminished effectiveness of insulin in reducing blood glucose levels. "In early insulin resistance, reduced GMIP activity may impair cellular structure and fat movement, promoting harmful fat buildup." (PMID 41056021, 2026).
liver cancer (1 paper, 2025). An epithelial or non-epithelial malignant neoplasm that arises from the liver. "In the LIHC_GSE98638 dataset, which includes 5,063 cells from 20 liver cancer patients, the analysis shows that in the LIHC microenvironment, GMIP expression is higher in immune cells, including CD8+ T cells." (PMID 40275529, 2025).
melanoma (1 paper, 2025). A malignant, usually aggressive tumor composed of atypical, neoplastic melanocytes. "In the GSE91061 melanoma cohort, melanoma patients with high GMIP expression had significantly better survival rates than those with low expression." (PMID 40275529, 2025).
ovarian carcinoma (1 paper, 2022). A malignant neoplasm originating from the surface ovarian epithelium. "Hsa_circ_0000497 and hsa_circ_0000918 may regulate ovarian cancer metastasis via their host genes, although neither SLAIN1 nor GMIP is reported in tumor metastasis." (PMID 35538537, 2022).
tumor (8 papers, 2017 to 2025). "GMIP's therapeutic potential is especially pronounced in BRCA‐mutated tumours, underscoring its relevance for novel anticancer interventions." (PMID 40275529, 2025). "Kaplan–Meier analyses of the top four tumor suppressor genes show that high expression of both GMIP and NKX2-1 is associated with significantly longer patient survival." (PMID 33227088, 2020). "GMIP is altered via frameshift deletion in one ASL tumor, and by nonsense mutation in one HCC tumor." (PMID 31796844, 2019). "By analysing the TCGA and GTEx databases, we further investigated the transcriptional levels of GMIP in tumours and compared them with normal tissues." (PMID 40275529, 2025). "Special attention was given to GMIP's genomic alterations across cancers and their prognostic significance, including its associations with CNV, DNA methylation, MSI, TMB and tumour immune infiltration." (PMID 40275529, 2025). "Through functional enrichment analysis of gene sequences, we explored the functional role of GMIP in tumours." (PMID 40275529, 2025). "The Rho pathway involving GMIP is highly associated with cancer, where RhoGAP activity is critical for the tumour‐suppressive function mediated by GMIP." (PMID 40275529, 2025). "The results underscore GMIP's significance in cancer initiation and progression, providing a foundation for future research on its role in tumour immunity and its potential as a target for novel immunotherapies." (PMID 40275529, 2025). "Our research suggests that GMIP, through its interactions with immune cells, can influence tumorigenesis and holds potential for predicting tumour progression and the effectiveness of antitumour therapies." (PMID 40275529, 2025). "High GMIP expression appears to be linked to a suppressive TME and weakened immune responses, potentially promoting tumour escape and progression." (PMID 40275529, 2025). "To further investigate the biological significance of GMIP in these tumours, we performed GSVA analysis." (PMID 40275529, 2025). "The findings indicated that GMIP expression in most TCGA tumours was positively correlated with the infiltration levels of B cells, CAF, CD4+ T cells and NKT cells, while it was negatively correlated with the infiltration levels of MDSCs." (PMID 40275529, 2025). "Future research should investigate GMIP's regulatory role in the tumour microenvironment and MSI, as well as its potential to predict immunotherapy efficacy, enabling stratification for patients receiving checkpoint blockade therapy." (PMID 40275529, 2025). "ESTIMATE analysis revealed that GMIP expression in the TME of 33 tumours is negatively correlated with stromal, immune and ESTIMATE scores, indicating its key role in TME regulation." (PMID 40275529, 2025). "GMIP's role in the Rho pathway, particularly its RhoGAP activity, is crucial for its tumour‐suppressive function." (PMID 40275529, 2025). "By comparing GMIP expression in tumour and normal tissues, we evaluated its distribution, prognostic impact and links to genomic stability and immune cell infiltration." (PMID 40275529, 2025). "Similarly, in NSCLC tumour tissues, GMIP shows a strong spatial correlation with the M2 macrophage markers CD163 and CD68." (PMID 40275529, 2025). "This contrasts with the traditional view that GMIP is suppressed in aggressive tumours and suggests it may have diverse roles depending on the cancer type." (PMID 40275529, 2025). "GMIP staining is weak in normal breast tissues but shows a moderate level in tumour tissues." (PMID 40275529, 2025). "Moreover, our spatial transcriptomic analysis demonstrates that in LIHC tumour tissues, GMIP spatially overlaps significantly with the CD8+ T cell markers CD8A and CD8B." (PMID 40275529, 2025). "The TISCH database identified primary GMIP‐expressing cell types in the tumour microenvironment." (PMID 40275529, 2025). "This article reviews the progress of GMIP research in different tumours." (PMID 40275529, 2025).
tumor (continued). "Our findings underscore GMIP's pivotal role in tumour immune regulation." (PMID 40275529, 2025). "Additionally, we conducted a genome‐wide analysis to assess GMIP's associations with DNA methylation, copy number variation (CNV), tumour mutation burden (TMB), microsatellite instability (MSI) and immune infiltration." (PMID 40275529, 2025). "FLOT and GMIP are associated with cytoskeletal organization and signal transduction, while PFKL plays a key role in glycolysis, suggesting enhanced metabolic and structural adaptability of platelets in the tumor microenvironment." (PMID 39001461, 2024). "GMIP is hypermethylated by this pathway and has tumor suppressor properties." (PMID 33227088, 2020). "Our analysis revealed a statistically significant positive correlation between GMIP expression and the StromalScore, ImmuneScore and ESTIMATE score, especially in tumours where these scores were more prominent." (PMID 40275529, 2025). "To identify the primary cell types expressing GMIP in the tumour microenvironment (TME), we performed a single‐cell analysis of GMIP across 78 cancer datasets." (PMID 40275529, 2025). "One of the hypermethylated genes, Gem Interacting Protein (GMIP), displays tumor suppressor properties." (PMID 33227088, 2020). "Conversely, genes such as FLOT, GMIP, and PFKL showed marked upregulation in tumor samples." (PMID 39001461, 2024). "GSEA analysis revealed that high GMIP expression is enriched in immune regulatory processes, including T cell activation, TNF regulation, neutrophil function and antigen processing and presentation—key pathways involved in tumour cell stress response, repair and cell cycle regulation." (PMID 40275529, 2025). "Moreover, we have uncovered new genes affected by frameshift MSI events in MSI-prone tumours as well as in tumour types not frequently affected by MSI (for example, FAM129A, GMIP and NEK3 in BRCA, and DPYSL2 and ALPK2 in OV)." (PMID 28585546, 2017).
cancer (6 papers, 2020 to 2025). A tumor composed of atypical neoplastic, often pleomorphic cells that invade other tissues. "GMIP exhibits significant associations with TMB in seven cancer types and MSI in five, indicating its potential role in modulating immune checkpoint inhibitor response." (PMID 40275529, 2025). "The expression levels of GMIP across various cancer types were analyzed using data from the TCGA database, and the association between GMIP expression and cancer prognosis was examined." (PMID 40275529, 2025). "GMIP‐associated diseases were identified using Open Targets, with red dashed lines denoting cancer associations." (PMID 40275529, 2025). "Our study further suggests that GMIP‐targeted strategies could present new opportunities for drug development in BRCA‐deficient cancers and LIHC‐deficient cancers." (PMID 40275529, 2025). "In 33 types of cancer, GMIP was highly correlated with MMR gene mutations, except for READ and UCS." (PMID 40275529, 2025). "Subsequently, samples were divided into WT (wild‐type), Amp (amplification) and Dele (deletion) groups, and we investigated the survival differences among CNV and GMIP genotypes in each cancer type." (PMID 40275529, 2025). "Subsequently, using TIMER2.0, we analysed the differences in GMIP mRNA expression between cancer tissues and adjacent normal tissues." (PMID 40275529, 2025). "In the pan‐cancer analysis, the Spearman correlation between GMIP CNV and mRNA expression was assessed." (PMID 40275529, 2025). "As research into GMIP and its regulatory network progresses, we anticipate breakthroughs in cancer diagnosis, treatment and prevention, fostering more targeted solutions and advancing the development of precision medicine and personalised therapy." (PMID 40275529, 2025). "GSVA analysis further confirmed GMIP's involvement in immune‐related pathways across different cancer types, offering new insights into its role as an immune modulator." (PMID 40275529, 2025). "Our integration of multiple databases (TCGA and GTEx) provides a more comprehensive and reliable assessment of GMIP expression patterns across diverse cancer types." (PMID 40275529, 2025). "To explore GMIP's role in 33 cancers, we analysed its co‐expression with stromal, immune and ESTIMATE scores, mismatch repair (MMR) markers and immune‐related genes." (PMID 40275529, 2025). "In this study, we identified GMIP as a robust pan‐cancer prognostic biomarker, capable of predicting immunotherapy outcomes." (PMID 40275529, 2025). "This pan‐cancer analysis reveals GMIP's critical functions at various stages of tumorigenesis and progression." (PMID 40275529, 2025). "Since cell migration is critical for metastasis, GMIP's regulation of RhoA is particularly important for cancer cell migration." (PMID 40275529, 2025). "GMIP belongs to the ARHGAP family of genes, and its family member DLC1 has been reported to be highly associated with cancer." (PMID 40275529, 2025). "GMIP mRNA is significantly upregulated in 13 cancers (e.g., BRCA, BLCA and CESC), while it is significantly downregulated in COAD, KICH and LUSC." (PMID 40275529, 2025). "Based on GMIP expression levels in different cancer types, we divided the samples into low and high expression groups and conducted GSEA and GSVA analyses to reveal the biological processes associated with GMIP." (PMID 40275529, 2025). "To explore GMIP's biological function and mechanism, we knocked down GMIP in the MCF‐7 cancer cell line and SK‐Hep‐1 cell line using siRNA." (PMID 40275529, 2025). "Currently, most studies on the relationship between GMIP and cancer focus on specific cancer types, while its role across various cancers remains underexplored." (PMID 40275529, 2025). "Our findings also offer insights into GMIP's potential role in cancer immunity and its implications for future immunotherapy strategies." (PMID 40275529, 2025). "GMIP exhibits differential expression across multiple cancer types, demonstrating significant prognostic implications." (PMID 40275529, 2025).
cancer (continued). "Functional studies suggest that GMIP inhibition reduces cancer cell proliferation and migration." (PMID 40275529, 2025). "We first analysed GMIP expression across various cancers using TCGA and GTEx data." (PMID 40275529, 2025). "In conclusion, GMIP exerts a broad and profound influence across multiple cancers." (PMID 40275529, 2025). "Through RhoA regulation, GMIP impacts cytoskeletal stability and reorganisation, affecting cell morphology, migration, division and adhesion—key processes in tissue development, wound healing and cancer metastasis." (PMID 40275529, 2025). "This multidimensional analysis approach could reveal new therapeutic strategies where specific miRNAs could be employed to modulate GMIP expression, potentially enhancing the efficacy of cancer treatments." (PMID 40275529, 2025). "In addition, the reduction in GMIP expression also markedly weakened the migration ability of cancer cells." (PMID 40275529, 2025). "Although research on GMIP remains limited, studies suggest its potential role in cancer." (PMID 40275529, 2025). "We subsequently analysed the predictive role of GMIP in the ICI cancer cohort." (PMID 40275529, 2025). "Thus, GMIP may act as an oncogene in some cancers, though its role may vary and requires further investigation." (PMID 40275529, 2025). "GMIP was significantly downregulated in ACC, DLBC and THYM, but upregulated in most other cancer types." (PMID 40275529, 2025). "Three proteins have not previously been associated with FTC, but are related to thyroid function or other types of cancer, namely, major vault protein (MVP), GEM‐interacting protein (GMIP) and galectin‐9 (LGALS9)." (PMID 35194950, 2022). "Apart from BIRC5, GMIP, IFI16, and TCIRG1, other genes didn’t show significant differences in individual cancer stages." (PMID 35237298, 2021). "Next, we explored the correlation between GMIP CNV and survival outcomes in different cancer types." (PMID 40275529, 2025).
neurodevelopmental disorder (1 paper, 2020). A behavioral and cognitive disorder with onset during the developmental period that involves impaired or aberrant development of intellectual, motor, or social functions. "Other genes, such as GMIP, NEK1, TFPT, CELSR3, and TTC21A, also showed interactions with ASD or other neurodevelopmental disorder-related genes in each gene network in the previous studies." (PMID 33374967, 2020).
GMIP also shares sentences with these, for which no sentence is quoted: adrenocortical carcinoma (1 paper); Alzheimer disease (1); bipolar disorder (1); major depressive disorder (1); ovarian serous cystadenocarcinoma (1); Tics (1).